RNU6-815P (RNA, U6 small nuclear 815, pseudogene)
Gene: Small nuclear RNA gene on chromosome 3 (20,507,644 to 20,507,756, reverse strand). Ensembl gene ENSG00000206807.
Homologues: Orthologues: chimpanzee U6 (99% identical), macaque U6 (80% identical), rabbit U6 (73% identical). Paralogues in human: RNU6-393P (81% identical), RNU6-1060P (81% identical), RNU6-1122P (81% identical), RNU6-1152P (81% identical), RNU6-166P (81% identical), RNU6-41P (81% identical), RNU6-820P (81% identical), RNU6-1029P (80% identical), RNU6-15P (80% identical), RNU6-48P (80% identical), RNU6-536P (80% identical), RNU6-562P (80% identical), and 1288 more.